ENSG00000293600 (novel protein)
Synonyms: SLC35A4-MP; LOC131768270
Gene: Protein-coding gene on chromosome 5 (140,564,446 to 140,569,100, forward strand). Ensembl gene ENSG00000293600.
Homologues: Orthologues: chimpanzee SLC35A4 (99% identical), mouse Gm58354 (89% identical), zebrafish si:ch73-42p12.2 (64% identical).